IKZF1 (IKAROS family zinc finger 1)
Description:
Transcription regulator of hematopoietic cell differentiation. Binds gamma-satellite DNA. Plays a role in the development of lymphocytes, B- and T-cells. Binds and activates the enhancer (delta-A element) of the CD3-delta gene. Repressor of the TDT (fikzfterminal deoxynucleotidyltransferase) gene during thymocyte differentiation. Regulates transcription through association with both HDAC-dependent and HDAC-independent complexes. Targets the 2 chromatin-remodeling complexes, NuRD and BAF (SWI/SNF), in a single complex (PYR complex), to the beta-globin locus in adult erythrocytes. Increases normal apoptosis in adult erythroid cells. Confers early temporal competence to retinal progenitor cells (RPCs) (By similarity). Function is isoform-specific and is modulated by dominant-negative inactive isoforms.
Synonyms: IK1; IKAROS; LYF1; ZNFN1A1; hIk-1; LyF-1; Hs.54452; PPP1R92; CVID13; PRO0758
Tractability: Small molecule: a structure with a bound ligand is known; a high-quality ligand is known. PROTAC: it is named in the literature on targeted protein degradation; UniProt records ubiquitination sites on it; ubiquitination databases record sites on it; its protein half-life has been measured; a small molecule that binds it is known.
Target class: Transcription factor
Chemical probes: Iberdomide
Gene: Protein-coding gene on chromosome 7 (50,303,412 to 50,405,101, forward strand). Ensembl gene ENSG00000185811.
Subcellular location: Nucleus; Nucleus (Isoform Ik2); Cytoplasm (Isoform Ik6)
Subcellular location (Human Protein Atlas): Nucleoplasm; Cytosol
Pathways (Reactome):
Chromatin organization: Interaction of NuRD complexes with transcription factors
Signal Transduction: NOTCH3 Intracellular Domain Regulates Transcription
Gene Ontology:
Molecular function: DNA binding; protein binding; protein domain specific binding; DNA-binding transcription factor activity; RNA polymerase II cis-regulatory region sequence-specific DNA binding
Biological process: erythrocyte differentiation; lymphocyte differentiation; mesoderm development; negative regulation of DNA-templated transcription; regulation of transcription by RNA polymerase II
Cellular component: nucleoplasm; nucleus; pericentric heterochromatin; protein-containing complex; cytoplasm
Genetic constraint (gnomAD): Loss-of-function variants: 9 observed, 49.06 expected, observed/expected ratio (o/e) 0.18, 90% interval 0.11 to 0.32. The upper end of that interval is the gene's LOEUF score, 0.32, which puts it in group 1 of 6, group 1 being the genes least tolerant of losing a copy. Missense variants: 466 observed, 717.73 expected, observed/expected ratio (o/e) 0.65, 90% interval 0.6 to 0.7. Synonymous variants: 277 observed, 289.2 expected, observed/expected ratio (o/e) 0.96, 90% interval 0.87 to 1.06.
Gene-disease validity (ClinGen):
ClinGen rates the evidence that IKZF1 causes each of these diseases.
pancytopenia due to IKZF1 mutations (autosomal dominant): Definitive. Any syndrome with combined immunodeficiency in which the cause of the disease is a mutation in the IKZF1 gene.
autoimmune disease (autosomal dominant): Moderate. A disorder resulting from loss of function or tissue destruction of an organ or multiple organs, arising from humoral or cellular immune responses of the individual to their own tissue constituents.
Cancer hallmarks: genome instability and mutations; escaping programmed cell death (suppresses); change of cellular energetics; invasion and metastasis (promotes); suppression of growth (promotes); tumour promoting inflammation; invasion and metastasis (suppresses); escaping programmed cell death; escaping immune response to cancer
Homologues: Orthologues: chimpanzee IKZF1 (100% identical), macaque IKZF1 (100% identical), rat Ikzf1 (93% identical), mouse Ikzf1 (92% identical), pig IKZF1 (89% identical), guinea pig IKZF1 (89% identical), dog IKZF1 (88% identical), rabbit IKZF1 (86% identical), tropical clawed frog ikzf1 (73% identical), zebrafish ikzf1 (67% identical), Drosophila melanogaster CG14442 (8% identical), Drosophila melanogaster CG14440 (5% identical). Paralogues in human: IKZF3 (53% identical), IKZF2 (50% identical), IKZF4 (49% identical), ZNF567 (17% identical), ZNF639 (17% identical), ZNF350 (16% identical), ZNF649 (16% identical), ZNF613 (16% identical), ZNF382 (15% identical), ZNF821 (13% identical), ZNF564 (13% identical).
Diseases named in the same sentence as IKZF1 in open-access papers:
IKZF1 is named in the same sentence as 157 diseases in open-access papers, as found by Europe PMC text mining. Sharing a sentence is not in itself a finding about the gene and the disease. The quoted sentences say what the papers report.
leukemia (104 papers, 2010 to 2025). A malignant (clonal) hematologic disorder, involving hematopoietic stem cells and characterized by the presence of primitive or atypical myeloid or lymphoid cells in the bone marrow and the blood. "Germline IKZF1 variants associated with leukemia predisposition also directly influence responsiveness of leukemia cells to chemotherapy." (PMID 39589495, 2025). "This indicates that a large number of genes aberrantly expressed in IKZF1-mutated leukemia are highly sensitive to IKZF1 dosage, and dependent on IKZF1/NuRD for repression." (PMID 39437550, 2025). "This is partly due to their association with inborn errors of the immune system, thrombocytopenia, and/or predisposition to leukaemia (IKZF1 and IKZF3) and to somatic defects that are frequently occurring in haematological malignancies (IKZF1 and IKZF2)." (PMID 39406892, 2024). "This fact suggests that IKZF1 can be considered a predisposing gene for the onset of leukemia since, both in vivo and in vitro, these germline variants trigger leukemogenesis processes." (PMID 36834692, 2023). "IKZF1 mutation will lead to the obstruction of lymphocyte differentiation and development, resulting in leukemia." (PMID 35419036, 2022). "The co-existence of PAX5, CDKN2A, and IKZF1 mutations classifies this leukemia as “Ikaros plus” high-risk ALL30." (PMID 35115489, 2022). "In this study, we used inducible expression of wild type IK1 in IKZF1-mutated human Ph+ B-ALL cell lines to study Ikaros tumor suppressor mechanisms in leukemia." (PMID 36278683, 2022). "We previously reported that leukemias harboring deletions or mutations affecting the B-cell transcription factor IKZF1 exhibit a tumor cell intrinsic resistance to glucocorticoids (GCs), one of the cornerstone drugs used in the treatment of ALL." (PMID 36119546, 2022). "For example, mutations of IKZF1–3 in leukemias are associated with poor prognosis, mainly caused by the disruption of lymphocyte fates." (PMID 36353107, 2022). "Of the genes mentioned, a role for the IKZF1 gene as a tumor suppressor has been established in both pediatric and adult leukemia, where a number of high-risk B-ALL subtypes harbor IKZF1 deletions or mutations." (PMID 36278683, 2022). "Recently, germline IKZF1 has also been characterized as a leukemia predisposition gene, where adverse germline IKZF1 variation has been found in familial pediatric ALL and occurs in approximately 1% of B-ALL patients." (PMID 34439222, 2021). "IKAROS (encoded by the IKZF1 gene) is a master regulator of lymphoid hematopoiesis and a tumor suppressor in leukemia." (PMID 33807974, 2021). "Genetic and functional abnormalities of IKZF1, including deletion of a single Ikaros, were regarded as new prognostic indicators for high-risk leukemia in clinical trials (NCT00993538; NCT03709719, NCT01431664)." (PMID 34950704, 2021). "The Ikzf1 locus encodes the lymphoid specific transcription factor Ikaros, which plays an essential role in both T and B cell differentiation, while deregulation or mutation of IKZF1/Ikzf1 is involved in leukemia." (PMID 32453736, 2020). "Leukemia-associated alternative splicing of IKZF1 can result in proteins with loss of one to four copies of its N-terminal zinc finger domains (N-ZnF)." (PMID 33126432, 2020). "Along with loss of IKZF1 and/or Ik-6 proteins in the leukemia cells, the nuclei underwent nuclear punctations as well as fragmentation reflecting apoptosis." (PMID 33126432, 2020). "IKZF1 genetic and functional abnormalities were also studied and considered as novel prognostic biomarkers for high-risk leukemia in several clinical trials (NCT00993538; NCT03709719, NCT01431664)." (PMID 32085659, 2020). "Burkhardt asserted that the combined cytogenetic MLL with a homozygote variant IKZF1 allele (rs1197867) increases infant leukemia risk." (PMID 31604453, 2019).
leukemia (continued). "In MPN, hemizygous loss of IKZF1 was detected in 21% of post-MPN leukemia and in 0.2% of chronic phase MPN indicating oncogeneic properties of IKAROS defects." (PMID 21646683, 2011). "In homozygous mutant mice deleted for the N-terminal zinc finger DNA binding domain of IKZF1 loss of expression leads to arrest of lymphocyte development at its earliest recognizable stage followed by rapid development of leukemia." (PMID 21307401, 2010). "Hence, genes identified here as direct targets of early repression by IKZF1 and NuRD in pre-B cells are critically dependent on IKZF1 for repression, and become aberrantly expressed in IKZF1-mutated leukemia." (PMID 39437550, 2025). "Nevertheless, when crossed to additional leukemia predisposing backgrounds (e.g. Ebf1 or Ikzf1, Stat5b or BCR-ABLp190) or challenged through external stressors (e.g. infection exposure or antibiotics) Pax5± mice develop an aggressive BCP-ALL that closely resembles the human disease." (PMID 40394211, 2025). "Germline mutations in IKZF1 have been associated with leukemia predisposition." (PMID 38255194, 2024). "The leukemia-associated transcription factor Ikzf1 was marked by two CISs." (PMID 36950387, 2023). "Indeed, combined pharmacological inhibition of AKT and ERK signaling effectively reversed GC resistance in IKZF1-deficient leukemias." (PMID 36119546, 2022). "In addition to mice mutated in Pax5 or Ikzf1, Irf4/Irf8−/−, and Irf4/Spi1−/− mice have been shown to develop leukemia early in life at a high incidence." (PMID 35459909, 2022). "IKZF1 played a key role in lymphopoiesis and also was a predisposition gene of leukemia." (PMID 34568071, 2021). "Targeting Ikaros-regulated signaling pathways could be a highly effective therapeutic approach in high-risk leukemias that are characterized by Ikaros genetic inactivation (IKZF1 haploinsufficiency due to deletion of one IKZF1 allele)." (PMID 32085659, 2020). "Papaemmanuil and colleagues showed a functional effect for rs4132601, which is in complete linkage disequilibrium with rs11978267, since each additional copy of the variant allele resulted in greater attenuation of IKZF1 mRNA expression, and consequently induced leukemia." (PMID 31604453, 2019). "There were 26 deaths in IKZF1 deletion cohort, 20 from leukemia and 6 from other causes." (PMID 27067989, 2016). "This hypothesis is mostly based on the circumstantial evidence that the other main subtype of ALL with frequent IKZF1 mutations are the Ph-like leukemias." (PMID 24724051, 2014). "Interestingly, IKZF1 is one of most important transcription factors involved in hematopoietic development, mutations and deletions of this gene are frequently observed in leukemia cells of B-ALL patients." (PMID 30697230, 2018). "The demonstration here that Runx activation is virtually essential for MYC transformation of early murine T-cell lymphoma suggests that it may be fruitful to examine the requirement for RUNX function in human leukaemia/lymphomas driven by amplified MYC or NOTCH/IKZF1 mutations." (PMID 24586197, 2014). "Together, these observations indicate that ERG is a direct IKAROS target and that its repression in B-ALL reflects restoration of a developmental silencing program normally lost in IKZF1-mutated leukemias." (PMID 41509392, 2025). "The molecular insights uncovered for IKZF1-mediated transcriptional repression in pre-B cells are therefore likely to inform mechanisms of deregulation in leukemia." (PMID 39437550, 2025). "On the other hand, our findings allow a better understanding of the role of BTG1 and IKZF1 deletions in modulating glucocorticoid response, thus helping to unravel the resistance phenomenon in leukemia cells displaying this genotype." (PMID 39095315, 2024).
leukemia (continued). "To evaluate the function of highly recurrent IKZF1 variants in a cellular context, we performed in vitro experiments to assess the impact of different variants on IKAROS activities and leukaemia cell phenotypes." (PMID 37345307, 2023). "With regards to large-scale copy number aberrations, trisomy 21 was moderately enriched in Late-Pro leukemias (n = 5/22, 23%; P = 0.020) and was found to be mutually exclusive with IKZF1 losses (FDR-adjusted P = 0.039)." (PMID 37337105, 2023). "Although IKZF1 alterations were present among all transcriptomic subtypes, bi-allelic losses were significantly enriched in Inter-Pro leukemias (n = 7/8, 88%; P = 2.0 × 10−7)." (PMID 37337105, 2023). "IKZF1 gene lesions that disrupt the role of lymphoid transcription factors influence the regulation of its target genes, whose activity is crucial for leukemia development and/or progression." (PMID 36834692, 2023). "Inter-Pro leukemias were also enriched for the dominant negative Ik6 deletion of IKZF1, which lacks the DNA binding domain (62%, 36% and 17% in Inter-Pro, Late-Pro and Early-Pro, respectively; P = 0.012)." (PMID 37337105, 2023). "Insight into this question came when it was revealed that alternative transcription initiation sites are used at the Notch1 gene in Ikzf1-/- and E2a-/- leukemias." (PMID 35514954, 2022). "One of the leukemias harbored additional deletions in PAX5 and IKZF1, thus can be classified as IKAROS plus similar to the spontaneous leukemia that was developed after IL7RAins transduction." (PMID 35115489, 2022). "IKZF1 is an important TF for the development of lymphocytes and has previously been connected to leukemia and autoimmune diseases." (PMID 36699378, 2022). "This leukemia is characterized by a single-copy deletion of the IKZF1 (IKAROS) tumor suppressor and increased activation of the PI3K/AKT/mTOR pathway." (PMID 33531656, 2021). "Our results identified a subgroup of cases clustering with known leukemia subtypes, e.g., DUX4-positive, and subgroups characterized by mutations in PAX5 and IKZF1, resulting in more cases being assigned to a defined subgroup." (PMID 34830809, 2021). "On the other hand, the mutational alleles on IKZF1 (chr7:50382590, G>A, p.G158S) and RB1 (chr13:48409776, T>C) are extremely concentrated in relapsed leukemia cells, indicating these mutations raised during late phase of leukemia progress." (PMID 33408321, 2021). "In the SUP-B15 leukemia cell line, we noted novel IKZF1 transcripts that include both an Ik-6 splice and a transcript with a 14 base pair insertion at the C-terminus." (PMID 33126432, 2020). "Gene expression analysis of mouse models and primary human leukemia suggested that reduced function of PAX5 increased the ability of an oncogenic form of IKZF1 or ETV6-AML to modulate gene expression." (PMID 31381561, 2019). "It has been mentioned that the IK6 isoforms of IKZF1 and DNA-binding domain point mutations in mouse models of BCR-ABL1-positive leukemia resulted in dasatinib resistance, cellular mislocalization, and the induction of stem cells." (PMID 31096545, 2019). "For example, while Ikzf1 was affected far more often in murine T-ALL, IKZF1 is recurrently mutated or deleted in relapsed human ALL and in certain high-risk leukemia subtypes at diagnosis." (PMID 31199785, 2019). "In this study, we analysed the archived gene expression profiling datasets of patients with leukaemia and uncovered the stem cell program that was activated in leukaemic cells with IKZF1 alterations." (PMID 29743561, 2018). "All together our data contribute to the knowledge on the recently defined ERG-related leukemia subtype, that despite the presence of IKZF1 deletions are marked by an excellent prognosis." (PMID 28415578, 2017). "IKZF1 gene aberrations are associated with a poor outcome in B-ALL and have a high risk of relapse in leukemia." (PMID 28580304, 2017).